IGF1 (insulin like growth factor 1)
Diseases named in the same sentence as IGF1 in open-access papers (continued):
Sharing a sentence is not in itself a finding about the gene and the disease.
Insulin resistance (continued). "Since the liver is the major site of IGF-1 production, when steatosis develops lowering insulin sensitivity, the severity of steatosis at different stages of insulin resistance and metabolic syndrome seems to be correlated with worsened circulating IGF-1 levels." (PMID 26733412, 2016). "IGF-1 has structural and functional homology with insulin, and it has been suggested that insulin resistance might lead to increased IGF-1 bioavailability to compensate for reduced insulin action." (PMID 26568155, 2015). "Insulin resistance in diabetic patients may lead to cancer by directly affecting the cancer cells via overexpression of insulin-like growth factor 1(IGF1) and insulin receptor (IR) substrate proteins." (PMID 25652009, 2015). "The authors have showed that up-regulation of miR-190b could play a role for decreased IGF-1 that induce insulin resistance in hepatocellular carcinoma." (PMID 26141719, 2015). "Findings in one review agree with our results, reporting an increased risk of myomas with diabetes, stating that this is most likely mediated by insulin resistance, increased IGF-1 activity (a growth factor for fibroid cells in vitro), and elevated androgen levels." (PMID 25969688, 2015). "Hyperinsulinemia and insulin resistance, which characterize diabetes, and the consequent upregulation of the insulin-like growth factor-1/insulin receptor substrate-1 system, may also explain the association between diabetes and HCC." (PMID 26074956, 2015). "IGF-1 is known to counteract insulin resistance and is reduced after preterm birth." (PMID 25766465, 2015). "In addition, exercise has been reported to have a beneficial effect on tumor outcomes by reducing insulin resistance and insulin and IGF-1 secretion." (PMID 26458923, 2015). "IGF-1 concentration is directly related to insulin sensitivity, irrespective of confounders such as age, BMI, WHR or glucose tolerance status, but its association to insulin resistance seems U shaped." (PMID 24736741, 2014). "The hallmark of the metabolic syndrome is insulin resistance, and the resultant hyperinsulinemia leads to decreased concentrations of IGF binding proteins and increased levels of bioavailable insulin-like growth factor-1 (IGF-1)." (PMID 25052889, 2014). "The carcinogenic effects of insulin resistance in HCC may be the activation of insulin-like growth factor (IGF)-1 and 2 stimulated by compensatory hyperinsulinemia." (PMID 24765205, 2014). "Cross-sectional studies suggest that IGF-1 levels may be reduced in insulin resistance and type 2 diabetes." (PMID 24586785, 2014). "We suggest that the presence of visceral obesity is more important than insulin resistance in healthy obese and the effect of insulin resistance may be confounded by WC, and some measured (IGF-1) or unmeasured factors." (PMID 24616825, 2014). "As a potential regulator of IGF-1, we reasoned that expression of miR-190b might be involved in insulin resistance." (PMID 24586785, 2014). "Obesity and T2DM are multifaceted but characterized by peripheral insulin resistance and compensatory overproduction of insulin by the β cells of the islet leading to increase circulating levels of insulin and enhanced bioavailability of IGF-1." (PMID 23437362, 2013). "Insulin resistance leads to impaired insulin/IGF-1 signaling in skeletal muscle." (PMID 24382946, 2013). "One example of epigenetics is how uteroplacental insufficiency-induced intrauterine growth restriction (IUGR), which predisposes to adult onset insulin resistance, decreases postnatal IGF-1 mRNA variants and the gene elongation mark histone 3 trimethylation of lysine 36 of the IGF-1 gene (H3Me3K36)." (PMID 22548154, 2012). "In addition, insulin resistance increases the biological activity of IGF-1, an important endocrine and paracrine regulator of tissue growth and metabolism." (PMID 22312273, 2012).
Insulin resistance (continued). "We speculate that decreased H3Me3K36 of the IGF-1 gene in both maternal hyperglycemia and IUGR leads to decreased IGF-1 mRNA variant levels and contributes to the development of adult onset insulin resistance." (PMID 22548154, 2012). "According to a hypothesis presented by Penntinen, an increased plasma IL-2 concentration brings about a reduction of bioavailability of insulin-like growth factor-1, by reducing the production of androgenic hormones, thus contributing to insulin resistance." (PMID 23065486, 2012). "We speculate that H3Me3K36 of the IGF-1 gene is sensitive to the glucose level of the prenatal environment, with resultant alteration of IGF-1 mRNA expression and ultimately vulnerability to adult onset insulin resistance." (PMID 22548154, 2012). "Obesity and its related metabolic abnormalities, including insulin resistance, alterations in the insulin-like growth factor-1 (IGF-1)/IGF-1 receptor (IGF-1R) axis, and the state of chronic inflammation, increase the risk of colorectal cancer (CRC) and hepatocellular carcinoma (HCC)." (PMID 22312273, 2012). "Thus, genetically induced IGF-1 or insulin resistance in mice induces tau hyperphosphorylation, indicating that at least the tau part of AD pathology is enhanced by insulin resistance in vivo." (PMID 22654904, 2012). "Decreased H3Me3K36 of the IGF-1 gene occurred in both genders in our prior study of IUGR, and these findings were associated with decreased IGF-1 mRNA variant levels and adult onset insulin resistance in both genders." (PMID 22548154, 2012). "IGFBP1 sequesters IGF1 reducing bioavailability and an increased IGF1:IGFBP1 ratio and reduced IGFBP1 in serum is associated with obesity, hyperinsulinemia and insulin resistance in human studies and in women with PCOS." (PMID 21935484, 2011). "It has been hypothesized that, by lowering insulin levels, IGF-1 reduces insulin resistance and might thus be of therapeutical importance in physiological states that are associated with insulin resistance, such as type 2 diabetes." (PMID 20414467, 2010). "Severity of inflammatory lesions on the face, insulin sensitivity (homeostasis modeling assessment of insulin resistance), androgens and insulin-like growth factor-1 and its binding proteins were assessed at baseline and at eight weeks, a period corresponding to the school term." (PMID 22253996, 2010). "t10c12 CLA showed regulatory effects on various genes: lower expression levels of CA3 and IGF1 after t10c12 CLA treatment in the whole group could be a sign for a beginning insulin resistance." (PMID 19689798, 2009). "We could hypothesise that sunitinib treatment could interfere with the IGF-1 pathway, having a subsequent impact on insulin resistance." (PMID 18841151, 2008). "This study could provide insights to the role of insulin, insulin resistance, IGF-1 in carcinogenesis although a precise role and the extent of influence cannot be determined." (PMID 17953765, 2007). "However, well controlled studies in humans are essential to study the link between insulin resistance, hyperinsulinaemia, IGF-1 and carcinogenesis." (PMID 17953765, 2007). "Insulin resistance/sensitivity and free IGF-1 levels shall be determined in all subjects." (PMID 17953765, 2007). "First, the preserved levels of IGF-1 in the amino acid groups might contribute since increased levels of IGF-1 is shown to reduce insulin resistance." (PMID 17212815, 2007). "We postulate that hyperinsulinaemia which prevails during initial phases of insulin resistance (condition prior to overt diabetes) increases bioactivity of free IGF-1, which may contribute to process of carcinogenesis." (PMID 17953765, 2007). "In addition, insulin resistance prevalent in people with high VAI may impair exercise-induced IGF-1 signaling and affect skeletal muscle hypertrophy and bone matrix mineralization processes." (PMID 40638655, 2025).
Insulin resistance (continued). "While all PPIs have been associated with adverse metabolic effects—such as reduced serum magnesium and insulin-like growth factor-1 (IGF-1) levels—which may contribute to insulin resistance, impaired renal urate excretion, and systemic inflammation, lansoprazole appears to differ mechanistically." (PMID 40459644, 2025). "However, the results of our study may support the therapeutic potential of future work on brain insulin resistance in AD and highlight the potential for combination therapies involving IGF-1 to prevent or delay dementia in humans." (PMID 40283962, 2025). "Furthermore, insulin resistance promotes overproduction of insulin-like growth factor-1, which, upon binding to IGF-1R, activates mitogen-activated protein kinase and phosphatidylinositol 3 kinase signaling pathways that enhance the genesis and metastasis of ocular melanoma tumors." (PMID 40862816, 2025). "Hyperglycemia and insulin resistance are recognized promoters of pancreatic carcinogenesis through mechanisms such as providing excess energy to cancer cells, stimulating epidermal growth factors, and activating insulin-like growth factor 1 (IGF-1) receptor-mediated pathways." (PMID 41149448, 2025). "Considering the effects of leptin and IGF-1 on fetal insulin resistance and lipid metabolism, increased levels of leptin and IGF-1 are potential plasma biomarkers of increased fetal adiposity, which may predispose to infant obesity and metabolic dysfunction in later life." (PMID 40725173, 2025). "Insulin resistance, a common feature of obesity and type 2 diabetes, leads to compensatory hyperinsulinemia, which may stimulate cellular proliferation by activating the insulin-like growth factor-1 (IGF-1) axis." (PMID 41586238, 2025). "Therefore, it is possible that an increase in GHR level due to increased BMI and insulin resistance in individuals with T2D may attenuate GH activity in the liver to stimulate IGF-1 synthesis." (PMID 38421647, 2024). "Characterized by hyperglycemia and elevated insulin levels, insulin resistance promotes the interaction between insulin and insulin-like growth factor binding proteins (IGFBPs), increasing free IGF-1 levels, This, in turn, may influence cellular regulation and proliferation within thyroid tissue." (PMID 39444449, 2024). "Additionally, omega-3 PUFAs seem to counteract insulin resistance by improving mitochondrial function and bioenergetics as well as by modulating phospholipid membranes, but also by increasing serum levels of insulin-like growth factor 1 (IGF-1)." (PMID 38966419, 2024). "However, the myotrophic effect of IGF1 may be attenuated by insulin resistance in the case of increased adiposity." (PMID 39143422, 2024). "Emerging evidence suggests that low IGF-1 levels in obese individuals may increase the risk of nonalcoholic fatty liver disease, metabolic syndrome, and insulin resistance." (PMID 37111069, 2023). "Clinically, insulin resistance and altered IR signaling is linked to diseases such as diabetes, accelerated atherosclerosis, and fatty liver disease, whereas IGF1R mutations or IGF-1 deficiency cause pre- and postnatal growth retardation and specific defects in tissue growth, e.g., microcephaly." (PMID 36548088, 2023). "During puberty, with an increment in GH and IGF-1 levels, the sex hormones have a significant impact on the linear growth and enhance the intensity of fluctuation in GH; this rise in GH is higher in T1DM children and is considered the cause of high insulin requirement and insulin resistance." (PMID 37859903, 2023). "The clinical features of this disease are primarily caused by excess IGF-1 production, a hormone secreted in the liver in response to GH; in addition to the hypertrophic effects of IGF-1 on tissue, excess GH results in metabolic complications including insulin resistance." (PMID 36721176, 2023).
Insulin resistance (continued). "Additionally, adipose‐induced insulin resistance and insulin‐like growth factor‐1 (IGF‐1) production can lead to hyperglycemia, excess circulating steroid hormones, and elevated free fatty acid levels, all of which contribute to metabolic dysfunction and tumor progression." (PMID 35719035, 2023). "There is also evidence to suggest that insulin increases hepatic IGF-1 and IGFBP-3 production through direct regulation of the GH receptor, and thus, in patients with severe insulin resistance, IGF-1 deficiency may be due to both impaired hepatic production and accelerated IGF-I excretion." (PMID 36331627, 2023). "Therefore, treatments targeting abnormal glucose metabolism, insulin resistance, and IGF-1/IGF-1R signaling axis may exert potential therapeutic effects to decrease the tumor burden and the metastasis risks of intraocular malignancies." (PMID 36003786, 2022). "Indeed, obesity leads to insulin resistance with increased insulin and IGF-1 and hyperandrogenism." (PMID 35276950, 2022). "This phenomenon could be explained by a variety of metabolic abnormalities including hyperinsulinemia, insulin resistance, increased insulin-like growth factor-1 (IGF-1) level, dyslipidemia, augmented inflammatory cytokines, elevated leptin, as well as decreased adiponectin." (PMID 36230836, 2022). "Hyperinsulinemia is present in T2D due to insulin resistance, and supraphysiological levels are hypothesized to amplify insulin’s mitogenic effect, both through direct receptor activation and an increase in IGF-1 signaling, promoting the proliferation of malignant cells." (PMID 36139140, 2022). "Furthermore, peripheral insulin resistance might also be accompanied by central insulin resistance, IGF-1 resistance, and IRS-1 and IRS-2 dysfunction, presumably as a consequence of Aβ oligomers further contributing to cognitive decline." (PMID 35615716, 2022). "Prior studies have demonstrated that low-dose GH may have beneficial effects on insulin resistance and glucose homeostasis due to increased circulating IGF-1, while long-term GH treatment in high doses impairs insulin sensitivity and exacerbates insulin resistance." (PMID 36619543, 2022). "Besides, insulin resistance could also promote muscle atrophy by inhibiting IGF1/PI3K/AKT pathways, activating fork head box O transcription factor (FOXO), enhancing atrogin-1 and MuscleRING-Finger-1 effects." (PMID 36434541, 2022). "Insulin resistance inhibits β-oxidation, increases the supply of free fatty acids, and alters triglyceride transport, resulting in steatosis and suppression of the growth hormone (GH)-insulin-like growth factor 1 (IGF1) axis responsible for muscle protein synthesis." (PMID 36567835, 2022). "However, diabetes mellitus make it more complicated for the selection of the therapeutic treatments given the sustained hyperglycemia, hyperinsulinemia, insulin resistance (IR), and insulin-like growth factor-1 (IGF-1) play a role in cancer progression and promotion." (PMID 36671422, 2022). "Moreover, long-term diabetes may contribute to insulin resistance, which can promote the expression of growth hormone receptors and increase the production of insulin-like growth factor 1 (IGF-1) receptors." (PMID 36290805, 2022). "In our study, hsa-miR-26b-5p, hsa-let-7i-5p, hsa-miR-100-5p and hsa-miR-143-3p were found to be interacting with IGF1R and/or IGF1 gene, suggesting that these miRNAs might play a role in this insulin resistance metabolism, in addition to diabetic complications." (PMID 36506063, 2022). "However, increased circulating lipids due to decreased uptake in muscle could lead to insulin resistance, and insulin resistance in muscle could decrease anabolic signaling by insulin/IGF-1." (PMID 35159148, 2022). "Waist and WHI were associated with IGF-1 but not with other markers of insulin resistance." (PMID 36614866, 2022).
Insulin resistance (continued). "Finally, a reduced expression of Igf1 (in LIG, but also in IUS) could be related to an increased risk for insulin resistance and cardiovascular diseases." (PMID 36152882, 2022). "Insulin resistance results in hyperinsulinemia and hyperglycaemia which alongside chronic inflammation promotes endometrial tumorigenesis and metastasis by the direct pro-proliferative and anti-apoptotic effect of insulin and insulin growth factor (IGF-1) on endometrial cells." (PMID 35600348, 2022). "The connection between the IGF-1 signaling pathway and colorectal cancer (CRC) has been suspected more than 10 years due to observation of the association between CRC and lifestyle factors (mainly physical inactivity and obesity) mediated by insulin resistance and hyperinsulinemia via the IGF axis." (PMID 36295073, 2022). "Furthermore, even during the intermittent stages of stressful periods, the catecholamine and cortisol levels in patients with OSAHS are higher than those of individuals in the general population, thereby aggravating insulin resistance and lowering IGF-1 levels." (PMID 36120463, 2022). "This may be one mechanism for the link of IGF-1 and insulin resistance." (PMID 34485526, 2021). "Hence, we cannot exclude that insulin resistance was still present impeding an increase of IGF‐1." (PMID 33830548, 2021). "However, hyperinsulinemia due to obesity-related insulin resistance may also be related to elevated free IGF-1 levels in obese children." (PMID 33643970, 2021). "In addition, sedentary behaviour and obesity-related insulin resistance, higher circulating levels of insulin and glucose, and enhancement of insulin-like growth factor 1 (IGF-1) are likely to boost cancer growth through involvement in cell differentiation, proliferation and apoptosis." (PMID 33492550, 2021). "Studies, including ours, have suggested that prolonged exposure to hyperinsulinemia might induce common molecular defects in the insulin/IGF-1 signaling pathway leading to both peripheral and β-cell insulin resistance and therefore contribute to the development of T2DM." (PMID 32150819, 2020). "Indeed, in the present study, increasing IGF-1 level leading to significantly more insulin resistance but a lower waist circumference, resulted in more neurogenic activity, whereas decreasing IGF-1 levels resulted in less endothelial activity in the vasomotion analysis." (PMID 33633687, 2020). "In the present study, however, the changes in insulin resistance and the vasomotion domains were disconcordant, i.e. insulin resistance became worse, whereas the contribution of the neurogenic and endothelial vasomotion domains increased after increasing the GH dose to a high-normal IGF-1 level." (PMID 33633687, 2020). "Existing studies have shown that chronic hyperglycemia, oxidative stress, insulin resistance, advanced glycation end products, insulin-like growth factor-1, the use of hypoglycemic drugs, and other factors may play an important role in the pathophysiological process of diabetic osteoporosis." (PMID 33447176, 2020). "However, why some patients' glucose tolerance status fails to improve postoperatively and which factors are involved, such as GH, IGF-1, acromegaly remission status, pancreatic β-cell function, insulin sensitivity and insulin resistance (IR), remains unclear." (PMID 31736874, 2019). "Moreover, in a cross-sectional study including more than 30,000 individuals, the G allele of another longevity variant ofFOXO3 was associated with a decrease in concentration of circulating insulin-like growth factor-1 (IGF-1), a marker of insulin resistance and chronic disease." (PMID 30228872, 2018). "IGFBP-3 is the most abundant IGFBP in circulation and high IGFBP-3 may be a risk factor for insulin resistance in the development of T2D irrespective of IGF-1 levels." (PMID 29351335, 2018).